ABCB1 (ATP binding cassette subfamily B member 1)
Diseases named in the same sentence as ABCB1 in open-access papers (continued):
Sharing a sentence is not in itself a finding about the gene and the disease.
cancer (continued). "Our results indicate that HS-173 efflux mediated by ABCB1 and ABCG2 significantly contributed to the reduced efficacy of HS-173 in these cancer cells." (PMID 37048130, 2023). "The intracellular concentration of HS-173 was considerably lower in ABCB1-overexpressing NCI-ADR-RES and ABCG2-overexpressing S1-MI-80 cancer cells as compared to the parental OVCAR-8 and S1 cancer cells." (PMID 37048130, 2023). "In this study, we investigate the potential of repurposing furmonertinib, an epidermal growth factor receptor (EGFR) tyrosine kinase inhibitor (TKI), as a candidate for reversing MDR mediated by ABCB1 and ABCG2 in multidrug-resistant cancer cells." (PMID 37762275, 2023). "More importantly, oftentimes ABCB1 and/or ABCG2 overexpression gives rise to the development of multidrug resistance (MDR) in cancer cells." (PMID 37048130, 2023). "Several studies have reported that some PI3K inhibitors are able to reverse MDR mediated by ABCB1 and/or ABCG2 in cancer cell lines." (PMID 37048130, 2023). "Additional markers such as CD151, CD147, and drug transporter proteins (ABCG2/CD338), (MDR1/ABCB1/CD243) have been reported to interact and co-express with CD44 on cancer cells." (PMID 36834918, 2023). "ABCB1, also known as MDR1 or P-glycoprotein (P-gp), can be expressed in normal tissues; however, it is overexpressed in many cancers." (PMID 36831661, 2023). "CSCs efficiently express ABC transporter proteins, such as MDR1/ABCB1, MRP1/ABCC1, and ABCG2, that belong to multidrug resistance proteins and ensure cancer cells’ resistance to anticancer therapy." (PMID 37626893, 2023). "P-glycoprotein (P-gp, ABCB1) is an ATP-binding cassette (ABC) transporter that contributes to the development of multidrug resistance (MDR) in cancer cells." (PMID 37444569, 2023). "ABC transporters, such as ABCB1, are thought to promote MDR along with apoptosis evasion and are expressed by cancer stem cells that are responsible for cancer progression and recurrence." (PMID 36839934, 2023). "Side-population (SP) analysis is a widely used assay for isolating cancer cells with the ability to efflux DNA-binding fluorescent dyes via the ATP-binding cassette (ABC) transporters, such as BCRP/ABCG2 and MDR1/ABCB1." (PMID 36676146, 2023). "In resistant cancers, the overexpression of ABC transporters, such as ABCB1 (P-gp or MDR1), presents a significant obstacle to chemotherapy, since many chemotherapeutic agents are substrates of these transporters." (PMID 36839934, 2023). "A predominant approach for a modulator to overcome MDR mediated by ABCB1 and ABCG2 involves directly impeding the activity of ABCB1 and ABCG2 within multidrug-resistant cancer cells." (PMID 37762275, 2023). "LINC00355 induces chemotherapy resistance in cancer cells by regulating five downstream genes, namely HMGA2, ABCB1, ITGA2, WNT10B, and CCNE1 genes." (PMID 38125763, 2023). "USP24 increases the levels of ABC transporters ABCB1, ABCG2, and ezrin to enhance the pumping of taxol from cancer cells." (PMID 36694209, 2023). "Among the ABC transporters, two have gained more attention due to their clinical significance in cancer MDR: P-glycoprotein (P-gp), or ABCB1, and ABCG2." (PMID 37111745, 2023). "ATP-binding cassette transporters, including ABCB1 (P-glycoprotein) and ABCG2 (BCRP/MXR/ABCP), are pivotal in multidrug resistance (MDR) development in cancer patients undergoing conventional chemotherapy." (PMID 37762275, 2023). "The cytotoxicity of HS-173 in several pairs of ABCB1- and ABCG2-overexpressing cancer cell lines and the respective parental cell lines was established to elucidate the impact of ABCB1 and ABCG2 on the efficacy of HS-173 in cancer cells." (PMID 37048130, 2023). "Our data revealed that furmonertinib effectively resensitized NCI-ADR-RES and KB-V1 cancer cells, as well as MDR19-HEK293 cells, to ABCB1 substrates colchicine, vincristine, and paclitaxel in a concentration-dependent manner." (PMID 37762275, 2023).
cancer (continued). "In summary, our data show the interactions of HS-173 with ABCB1 and ABCG2, as well as providing experimental evidence that the overexpression of ABCB1 or ABCG2 in cancer cells is a novel mechanism of acquired resistance to the PI3K inhibitor HS-173." (PMID 37048130, 2023). "In contrast, tariquidar and Ko143 completely reversed MDR mediated by ABCB1 and ABCG2 in these cancer cell lines." (PMID 37048130, 2023). "Taken together, our results demonstrate that the efficacy of HS-173 was reduced by the drug-transport function of ABCB1 and ABCG2 in cancer cells." (PMID 37048130, 2023). "Methyl-cantharidimide plays a critical role in reducing cisplatin resistance at ABCB1- and ABCG2-overexpressing cancer cells." (PMID 37202806, 2023). "Among the various mechanisms contributing to the MDR phenotype in cancer, a significant factor is the high expression of ATP-binding cassette (ABC) drug transporters, particularly ABCB1 (P-glycoprotein/MDR1) and ABCG2 (BCRP/MXR/ABCP)." (PMID 38004460, 2023). "Prior to the elucidation of the compounds’ influence on the cell viability, we have determined the levels of ABCB1 and ABCG2 expression in different cancer cell lines." (PMID 38004447, 2023). "For example, USP24 positively regulates drug resistance partially by stabilizing ABC transporters, including ABCB1, ABCG1, and ABCC1, to pump out drugs from cancer cells." (PMID 36694209, 2023). "In this study, we investigated the modulatory effect of hydroxygenkwanin on ABCB1- and ABCG2-mediated MDR in multidrug-resistant cancer cells." (PMID 36361555, 2022). "Among the ABC transporter superfamily, P-glycoprotein (P-gp/ABCB1), multidrug resistance protein 1 (MRP1/ABCC1), and breast cancer resistance protein (BCRP/ABCG2) are considered to be the most closely related to MDR in cancer cells." (PMID 35565231, 2022). "ABCB1 and ABCC1 promote the MDR phenotype on a variety of cancer models, including the FEPS cell line." (PMID 35719932, 2022). "Moreover, previous studies have reported that paclitaxel is an excellent P-glycoprotein (ABCB1) substrate, and that multidrug resistance-associated protein 7 (MRP7/ABCC10) expression is a predictive biomarker for the resistance to paclitaxel in various types of cancer cells." (PMID 35141332, 2022). "Collectively, our data illustrate that BGJ 398, a selective FGFR inhibitor, effectively modulates an efflux of PTX and Dox from Tx-R cancer cells overexpressing ABC-transporters, in particular, ABCB1." (PMID 35327403, 2022). "In this study, we examine the interaction between hydroxygenkwanin, ABCB1, and ABCG2, which are two of the most well-characterized ABC transporters known to contribute to clinical MDR in cancer patients." (PMID 36361555, 2022). "Secondly, because cancer SP cells highly express three ATP-binding cassette (ABC) transporters, ABCB1 (also known as MDR1/P-glycoprotein), ABCC1, and ABCG2 (also known as BCRP), they are thought to be chemo-resistant tumor-initiating cells." (PMID 35659728, 2022). "In the current work, an aberrant increase in CREB1 phosphorylation was observed in MDR cells, and inhibition of CREB1 decreased ABCB1 expression and activity, indicating that CREB1 is a viable target for MDR reversal in cancer therapy." (PMID 36439493, 2022). "Among the selected cancer stemness genes, we found that TERT, MYC, CD44, BMI1, ABCB1 and ABCG2 were highly expressed in OCM1 cells compared to their expression in C918 cells, whereas the expression of ZEB1 was opposite to that of the stemness genes." (PMID 35404029, 2022). "Some key regulatory genes and proteins were modulated, such as ATP7A, ABCG2, ABCC1 and ABCB1 in response to EC-synthetic retinoids, suggesting that their expression may be under the regulation of retinoid signaling pathways with a potential role in diminishing cancer resistance and carcinogenesis." (PMID 36012706, 2022).
cancer (continued). "Due to the high drug‐loading rate of the self‐assembly and low affinity of RuZ for the ABCB1 and ABCG2 transporters, a high intracellular level of RuZ was retained in the MDR cancer cells." (PMID 34613635, 2022). "Rivoceranib, a potent inhibitor of vascular endothelial growth factor receptor 2 (VEGFR-2), has been shown to reverse ABCB1- and ABCG2-mediated resistance in cancer cells." (PMID 35327403, 2022). "CEP also interferes with other transporter proteins, such as ABCB1 (also known as MDR1 or P-glycoprotein), possibly by inhibiting the PI3K/Akt signaling pathway, leading to the downregulation of ABCB1 expression in cancer cells, which in turn reverses MDR." (PMID 36558061, 2022). "Numerous natural products are known to be capable of reversing MDR in ABCB1- and ABCG2-overexpressing multidrug-resistant cancer cells." (PMID 36361555, 2022). "As it was noted in the previous section, the overexpression of ATP-dependent efflux pumps, such as ABCB1, ABCB4 and ABCG2, is a common phenomenon in drug-resistant cancers and these genes were included in the “response to drug’’ process in our data." (PMID 36078127, 2022). "Consistently, knockdown of ABCB1 clearly decreased both cell viability and clonogenic growth capacity in chemotherapy‐treated MDR cancer cells." (PMID 35023619, 2022). "Given that BGJ 398 effectively inhibited the efflux of chemotherapeutic agents (Dox and PTX) from MDR-expressing cancer cells, we examined the drug-binding pocket (DBP) of ABCB1 as a potential binding site for this ligand." (PMID 35327403, 2022). "The ABC family members ABCB1, ABCC1, and ABCG2, which are related to drug resistance in several types of cancer, were first evaluated in MDA-MB-231 cells." (PMID 36291159, 2022). "Several members of the ABC family, such as ABCB1, ABCC2, and ABCG2, have been shown to contribute to the development of MDR in a variety of cancers." (PMID 36059609, 2022). "In an in vitro experiment, inhibition of SMAD3 C-terminal phosphorylation reversed ABCB1- and ABCG2-mediated multidrug resistance in cancer cell lines, E4BP4-mediated NK cell development, and tumor metastasis." (PMID 35085106, 2022). "ATP-binding cassette subfamily B member 1 (ABCB1) or P-glycoprotein (P-gp) and ATP-binding cassette subfamily G member 2 (ABCG2) play indispensable roles in cancer cell MDR." (PMID 36120340, 2022). "In summary, MRTX849 was found to overcome ABCB1-mediated MDR both in vitro and in vivo by specifically attenuating ABCB1 efflux activity in drug-resistant cancer cells." (PMID 36104708, 2022). "The decrease in ATP levels and its low affinity for the ABCB1 and ABCG2 transporters (which mediate MDR) significantly increase the retention of RuZ by MDR cancer cells." (PMID 34613635, 2022). "The overexpression of ABC transporters (ABCB1, ABCG2, and ABCC1), along with CYP3A4, is frequently observed in various cancer types." (PMID 36559089, 2022). "Of these, ABCB1 and ABCG2 appear to be the most important in the mediation of the MDR phenotype in cancer cells when overexpressed." (PMID 33573093, 2021). "Our results are consistent with and lend additional support to the notion that the expression levels of ABCB1 and SLFN11 are potential biomarkers for cancer cell line sensitivity to multiple drugs." (PMID 33858332, 2021). "ABC transporters including ABCB1, ABCC1, ABCC2, and ABCG2 are involved in the reduction of chemosensitivity in cancer cells." (PMID 34066059, 2021). "Hyperactivation of ABC transporter ABCB1 and induction of epithelial–mesenchymal transition (EMT) are the most common mechanism of acquired cancer chemoresistance." (PMID 33753859, 2021).
cancer (continued). "Even if a universal marker for Cancer Stem Cells (CSCs) identification remains undiscovered, CSCs often express distinctive markers like CD133, CD44, ABCB1/5 (CD243), ALDH1 and many others, though many of them are tissue- and tumor-related." (PMID 34055629, 2021). "ABC transporters, including ABCB1 and Subfamily G Member 2 (ABCG2), mediate drug efflux to attenuate the accumulation of chemotherapeutic drugs in cancer cells." (PMID 34198967, 2021). "On the contrary, a decrease in the stability of numerous transporters at the plasma membrane, such as ABCB1, ABCC1 (MRP1) or ABCG2 (BCRP), would be necessary to improve the efficiency of cancer treatments facing ABC transporter-mediated MDR." (PMID 33672718, 2021). "Numerous in vitro and in vivo studies have stated that the overexpression of ABCB1 is involved in mediating resistance to PTX and docetaxel in various types of cancers." (PMID 34360846, 2021). "ABC transporters, in particular ABCB1 and especially ABCG2, are abundantly expressed in hematopoietic progenitor cells and are overexpressed in cancer and CML stem cells." (PMID 34055641, 2021). "In conclusion, our results revealed a novel mechanism by which ABCB1 and ABCG2 actively transport citarinostat away from targeting HDAC6 in cancer cells." (PMID 33807514, 2021). "We found that the efficacy of citarinostat on attenuating the HDAC6 deacetylase activity and the induction of apoptosis correspond directly to the reduced accumulation of citarinostat in ABCB1- and ABCG2-overexpressing human cancer cells." (PMID 33807514, 2021). "As reported in many studies, genomic amplification of the chromosomal region 7q21, such as ABCB1 and SRI occurred in the multidrug-resistant cancers." (PMID 34869449, 2021). "The overexpression of P-glycoprotein (P-gp/ABCB1), an ATP-binding cassette (ABC) drug transporter, often contributes to the development of multidrug resistance (MDR) in cancer cells." (PMID 34350184, 2021). "From a translational perspective, steering the evolutionary dynamics of ABCB1 acquired resistance through the inhibition of metabolism or ECM may represent a novel therapeutic approach for ABCB1-mediated acquired resistance in HGSOC patients as well as for all ABCB1-driven MDR cancers." (PMID 34830797, 2021). "Among these transporters, ABCB1 (MDR1, P-pg), ABCG2 (BCRP), and ABCC1 (MRP1) are widely investigated in past 20 years which were well-related with MDR in cancer." (PMID 33593355, 2021). "Upregulation of ABCC1-5, ABCB1, and ABCG2 is the main reason for the development of multiple drug resistance in various cancers by excreting chemotherapy drugs out of cancer cells." (PMID 33782384, 2021). "ABC family members including ABCB1, ABCC1, ABCC2, ABCC3, and ABCG2 were critical for CDDP resistance of cancer cells." (PMID 33754002, 2021). "Acting as one of the main agents of MDR in cancers, the overexpression of ABC transporters such as ABCB1, ABCC1, and ABCG2 have been reported in CSCs that protect cells from cytotoxic agents." (PMID 34051847, 2021). "Aside from CD133+, which is also found in persister cancer cells, CD24-, CD44+, ABCB1+, ABCG2+ and ALDH+ are common phenotypic markers for CSCs." (PMID 35582031, 2021). "Most prominent and well-studied are ABCB1, ABCC1, and ABCG2, not only due to their contribution to the multidrug resistance (MDR) phenotype in cancer, but also due to their contribution to AD." (PMID 34977908, 2021). "In this study, we investigated the potential role of the multidrug efflux transporters ABCB1 and ABCG2, which are two of the most common mechanisms of acquired resistance to anticancer drugs, on the efficacy of citarinostat in human cancer cells." (PMID 33807514, 2021). "Rutaecarpine significantly sensitized ABCB1-overexpressing cancer cells MCF-7/ADR and A549/Taxol to ABCB1 transport substrates, compared with the resistance cells without rutaecarpine, and this sensitization occurred in a dose-dependent manner." (PMID 34572328, 2021).
cancer (continued). "It should be noted that other MDR-related ABC transporters such as ABCB1 and ABCC1 also actively mediate the drug resistance in cancer treatment." (PMID 34336849, 2021). "Overall, our results indicated that MCA's efficacy in ABCB1- and ABCG2-overexpressing and cisplatin resistant cancer cells is due to the induction of apoptosis and cell cycle arrest in the G0/G1 phase." (PMID 32676451, 2020). "In the present study, we investigated the effect of sitravatinib, a novel multitargeted receptor tyrosine kinase inhibitor, on human ABCB1 and ABCG2 in multidrug-resistant cancer cell lines." (PMID 31941029, 2020). "For example, overexpression of ATP-binding cassette (ABC) transporter family proteins, such as P-glycoprotein (MDR1/ABCB1) and multidrug resistance protein 1 (MRP1/ABCC1), enhances efflux of anti-cancer drugs from cells." (PMID 32151067, 2020). "Next, the potential effect of erdafitinib on the protein expression of ABCB1 was examined in ABCB1-overexpressing NCI-ADR-RES and KB-V-1 cancer cells." (PMID 32466597, 2020). "EC16-1/saporin, at nanomolar concentrations, significantly inhibited the cellular proliferation of parental and ABCB1- and ABCG2-overexpressing cancer cells." (PMID 32098067, 2020). "The findings based on our in vitro experiments led us to determine the effect of EC16-1/saporin in the parental and the ABCB1- and ABCG2-overexpressing cancer cells using mouse xenograft tumor models." (PMID 32098067, 2020). "ABCB1 expression correlated with ICEC0942 and THZ1 response, and ABCG2 expression with THZ2 response, in a panel of cancer cell lines." (PMID 31530935, 2020). "In the present study, we report the potential interactions of sitravatinib with ABCB1 and ABCG2 in human multidrug-resistant cancer cells." (PMID 31941029, 2020). "ABCB1, ABCB4, ABCG2, and ABCC2 are well-described markers of drug resistance development in many cancers." (PMID 31991882, 2020). "Chemoresistance is often associated with elevated expression of drug efflux pumps, so we analyzed the expression of ABCB1/MDR1 and ABCG2, two major p-glycoproteins commonly up-regulated in cancer stem cells (CSCs)." (PMID 32477461, 2020). "In a murine model system, EC16-1/saporin significantly inhibited the tumor growth in mice xenografted with parental and ABCB1- and ABCG2-overexpressing cancer cells." (PMID 32098067, 2020). "Our data suggest that sitravatinib re-sensitizes ABCB1- and ABCG2-overexpressing multidrug-resistant cancer cells by attenuating the drug transport function of ABCB1 and ABCG2." (PMID 31941029, 2020). "ATP-binding cassette (ABC) transporters, particularly, the ABCB1 and ABCG2 transporter, are mediators of multidrug resistance (MDR) in certain types of cancer cells." (PMID 33158067, 2020). "It has been well-established that the overexpression of the ABCB1 and/or ABCG2 transporters can produce MDR in cancer cells." (PMID 33158067, 2020). "The overexpression of ABCB1 and/or ABCG2 in cancer cells is known to contribute significantly to the development of multidrug resistance, an enormous challenge for scientists to overcome." (PMID 31941029, 2020). "Our data indicate that erdafitinib is equally effective in treating ABCB1- and ABCG2-overexpressing multidrug-resistant cancer cells as drug-sensitive cancer cells." (PMID 32466597, 2020). "ABCB1, ABCC1, and ABCG2 are ATP-binding cassette (ABC) transporters functioning as efflux pumps, lowering intracellular accumulation of various anti-cancer drugs." (PMID 33066132, 2020). "With ABCB1 as such a target gene, the overexpression of MACC1 in cells with activated Wnt/β-catenin signaling leads to increased resistance to anti-cancer therapies, including anthracyclines like doxorubicin." (PMID 32391276, 2020). "Further investigations revealed that the TRPC5-mediated Ca2+ influx induces the expression of the ATP-binding cassette subfamily B member 1 (ABCB1), a pump overproduced in cancer cells, responsible for the export of cytotoxic drugs." (PMID 32182937, 2020).